INS (insulin)
Diseases named in the same sentence as INS in open-access papers (continued):
Sharing a sentence is not in itself a finding about the gene and the disease.
insulinoma (continued). "Several authors have reported the use of intraoperative insulin monitoring during resection of insulinomas in adults, in an attempt to improve intraoperative resection and outcome." (PMID 17958895, 2007). "Intraoperative insulin levels of 172 U/dL were measured after initial identification of the insulinoma." (PMID 17958895, 2007). "When insulin levels drop more than 50% of baseline within several minutes of insulinoma resection, the surgery is considered successful." (PMID 17958895, 2007). "The insulinoma was enucleated laparoscopically, and rapid intra-operative insulin assay used to determine the success of the procedure." (PMID 17958895, 2007). "It determines the level of active insulin molecule in the serum and is checked before insulinoma enucleation and right after enucleation intraoperatively." (PMID 17958895, 2007). "Rapid determination of insulin levels with detection of C-peptide is a new modality for diagnosing insulinoma." (PMID 17958895, 2007). "This intraoperative radioimmunoassay for insulin yields results within several minutes and confirms complete resection of insulinoma." (PMID 17958895, 2007). "Tumors 1, 8, and 10 had high levels of insulin expression and came from patients with the clinical diagnosis of insulinoma." (PMID 15691381, 2005). "Tumor 9, which came from a patient with a clinical diagnosis of insulinoma had a high level of glucagon expression; the clinical diagnosis was apparently due to the other tumor (#8) which did have a high level of insulin expression." (PMID 15691381, 2005). "High concentrations of glucose did not affect membrane potential, transmembrane 45Ca fluxes, [Ca2+]i or insulin release by insulinoma cells." (PMID 2844219, 1988). "Insulinoma cells displayed a resting [Ca2+]i of 94 +/- 8 nM (n = 17) and released 104 +/- 15 ng insulin 10(-6) cells (n = 7) during 60 min incubations with uptake of 2.7 +/- 0.2 nmol 45Ca 10(-6) cells (n = 7)." (PMID 2844219, 1988). "Screening for islet autoantibodies (AABs), including glutamic acid decarboxylase (GADA), insulin (IAA), insulinoma-associated-2 (IA-2A), zinc transporter-8 (ZnT8A), and islet cell cytoplasmic autoantibodies (ICAs), was performed via chemiluminescence immunoassay (CLIA)." (PMID 42074878, 2026). "Total insulin levels were markedly elevated at 7,000 μU/mL (48,615.00 pmol/L), and free insulin levels were elevated at 24 μU/mL (166.68 pmol/L), which initially raised concern for an insulinoma." (PMID 41755959, 2026). "Insulinomas typically present with significantly elevated insulin levels." (PMID 39935661, 2025). "Four cases demonstrated insulin hypersecretion in multiple vascular territories, supporting a diagnosis of nesidioblastosis, while the remaining 3 cases showed insulin hypersecretion in a single vascular territory, consistent with insulinoma vs nesidioblastosis." (PMID 40799776, 2025). "Insulinomas are commonly encountered as solitary benign tumors, typically measuring less than 2 cm in diameter, while malignant insulinomas are larger in size, with an average size of about 4–5 cm in diameter, and they also have higher levels of insulin and C‐peptide in the serum." (PMID 39935661, 2025). "Only two tumors were clinically insulinomas, while three others were insulin IHC positive." (PMID 41312422, 2025). "Thus, both curative surgical resection and adjunct locoregional treatments support improved metabolic and nutritional outcomes in insulinoma patients by normalizing insulin levels, which, in turn, restores glucose homeostasis and allows for balanced nutrition." (PMID 40647278, 2025). "Conversely, suppression of PC results in decreased insulin expression in insulinoma cells." (PMID 41465472, 2025). "Canine insulinoma is an insulin-producing pancreatic neuroendocrine tumour with a poor prognosis." (PMID 40438247, 2025).
insulinoma (continued). "After a diagnosis of insulinoma has been established, non‐invasive imaging techniques such as computed tomography (CT) and magnetic resonance imaging (MRI) of the abdomen are employed to identify the origin of the abnormal insulin secretion." (PMID 40124204, 2025). "Additionally, dogs with insulinoma tend to gain weight after the condition develops due to anabolic effects of insulin on metabolism." (PMID 39828734, 2025). "In patients with insulinoma, definitive local therapies, such as surgery and locoregional interventions, play a pivotal role in stabilizing metabolism and nutrition by controlling the source of excess insulin secretion." (PMID 40647278, 2025). "Importantly, since both insulin-expressing populations were present in both the primary tumour and the metastasis, any novel therapeutic strategy in canine insulinoma would need to be effective at targeting both types of insulin-expressing cells." (PMID 40438247, 2025). "The most common type of functioning PanNET is the insulin-secreting PanNET, also called insulinoma." (PMID 39954168, 2025). "Furthermore, coumarins enhance insulin secretion in rat insulinoma (INS-1) cells, indicating its potential as a diabetic treatment." (PMID 40541990, 2025). "On the one hand, VDR knockdown was found to decrease Ins2 (insulin-encoding gene) expression and insulin secretion in mice as well as increase cytokine-induced cell death in INS-1 rat insulinoma cells and human-induced pluripotent stem cells differentiated into pancreatic β-cell-like cells." (PMID 39339785, 2024). "Similarly, large insulinomas are more often aggressive and the late symptomatology usually observed in those cases suggests relatively low or late-acquired insulin production." (PMID 39331358, 2024). "Despite the absence of insulin use and normal laboratory results for cortisol, TSH, blood count, and liver and kidney function, a fasting test revealed diminished C-peptide and insulin levels, ruling out insulinoma, exogenous insulin use, or β-cell hyperplasia." (PMID 38666048, 2024). "We investigated whether serotonin in nanomolar concentrations influenced insulin production and secretion in rat insulinoma INS-1E cells." (PMID 38999937, 2024). "When insulinoma occurs, the tumor’s beta cells release insulin autonomously." (PMID 39723310, 2024). "Insulinoma can present with recurrent hypoglycemic seizures, and it is very crucial to check for serum insulin and C-peptide levels during the hypoglycemic episode (critical blood glucose level); it is a totally reversible or correctable condition after localizing and resection of the lesion." (PMID 39070407, 2024). "Although previous studies using an immortalized mouse insulinoma β cell line (MIN-6) demonstrated a spinophilin-dependent regulation of M3 muscarinic receptor-dependent insulin secretion, the role of spinophilin in vivo in the intact pancreas has not been probed." (PMID 38630048, 2024). "To investigate whether inceptor binds insulin, we added insulin–biotin to the mouse insulinoma MIN6 cells and observed co-precipitation of inceptor with insulin–biotin." (PMID 39587340, 2024). "Antiglutamic acid decarboxylase, anti-insulin, and anti-insulinoma–associated antigen-2 antibodies were negative." (PMID 38745825, 2024). "In our series of patients ASVS provided important functional information and could successfully localize the origin of the elevated insulin levels, which were usually higher in localized insulinomas, then in nesidioblastosis." (PMID 39497809, 2024). "Insulinomas are rare insulin-secreting neuroendocrine neoplasms of the pancreas." (PMID 39497809, 2024). "INS-DRiP expression in human pancreas and insulinoma sections was tested by immunohistochemistry." (PMID 38596681, 2024).
insulinoma (continued). "HNRNPA2B1 is an RNA-binding protein involved in many post-transcriptional RNA regulation processes that has been shown to be differentially expressed upon glucose exposure in human EndoC-βH1 cells and to regulate intracellular and secreted insulin content in mouse insulinoma MIN6 cells." (PMID 38967666, 2024). "Contrary to glycosyloxyflavones (gossypin and rutin) the aglycones (quercetin, herbacetin and baicalein) not only support cell viability but also affect beta cells proliferation and support insulin production, thus restoring the functionality of insulinoma cells and beta cells organoids." (PMID 37872245, 2023). "Along these lines, we hypothesized that the heterogeneity of ion channels might involve uncontrollable insulin secretion of insulinoma compared with NFPNET." (PMID 37772258, 2023). "In the female, elevated levels of insulin, C‐peptide and pro-insulin together with pathological findings during a fasting test proved the presence of an insulinoma, which could be detected by Ga-68-DOTATOC-PET-CT in the pancreas." (PMID 36703082, 2023). "The preoperative elevated proinsulin levels and proinsulin/insulin molar ratio could predict the malignancy of insulinoma as well as ARX expression by IHC staining." (PMID 37251916, 2023). "Also, incubation of primary mouse islets and mouse insulinoma cells (MIN6) with mPS resulted in enhanced insulin secretion." (PMID 37490001, 2023). "In addition, although the association between the size of the pancreatic mass and a poor prognosis has been demonstrated only in human patients, with time the insulinoma can become larger with consequently higher insulin production." (PMID 37194422, 2023). "In summary, MCOLN1, ATP6V0E1, and ATP4A might enhance the insulin secretion of insulinomas by participating in regulating the function and TGF-beta signaling pathway." (PMID 37772258, 2023). "This indicates that the ion channel activity might play a crucial role in modulating insulin secretion from insulinoma." (PMID 37772258, 2023). "Abnormal insulin hypersecretion is a necessary condition of insulinoma diagnosis." (PMID 37772258, 2023). "Importantly, Rab26 also suppressed GLP-1-stimulated insulin secretion, indicating that Rab26 restricts the glucose-stimulated insulin secretion (GSIS) in pancreatic insulinoma cells." (PMID 37289842, 2023). "In order to develop an automated protocol to measure insulin secretion in the mouse insulinoma Min6 cell line, we first miniaturized the GSIS protocol in 384-well plates and validated that these cells do respond to glucose stimulation in these culture conditions." (PMID 36980190, 2023). "Another cell line derived from an insulinoma, CM, was derived from patient ascites and has been used for over 40 years, with positive data comparing its insulin secretion to cells, although these results have been the subject of controversy in more recent studies." (PMID 37568572, 2023). "In this case, the need for fine needle aspiration with an 18-gauge fine needle inserted into the suspicious lesion acting as a probe until the dome of the insulinoma is identified and a localized resection with serial measurement of insulin level intraoperatively is amenable." (PMID 37026903, 2023). "In both healthy humans and dogs, insulin secretion follows a circadian rhythm, which might be disrupted by the presence of insulinoma." (PMID 37194422, 2023). "Insulinoma is a rare pancreatic NEN (pNEN) that secretes insulin." (PMID 36950054, 2023). "Even if everolimus is not registered for this indication by the EMA and FDA, it could be used for uncontrolled insulinoma symptoms due to its direct suppressive role in insulin secretion." (PMID 37103745, 2023). "It has been suggested that the overexpression of GCK in canine insulinoma cells may partly explain why insulinomas secrete excessive amounts of insulin." (PMID 36288153, 2022).
insulinoma (continued). "Interestingly, transient knockdown of ALMS1 (siRNA-Alms1) in the β-TC-6 mouse insulinoma cell line resulted in constitutive insulin secretion independently of glucose concentrations." (PMID 35832432, 2022). "Using the most widely used cutoff values, 142 in 142, 140 in 140, and 90 in 93 of patients with insulinoma had end-of-fast insulin, C-peptide, and proinsulin concentrations of ≥ 3 μIU/ml (sensitivity, 100%), ≥ 0.6 ng/ml (sensitivity, 100%), and ≥ 5 pmol/l (sensitivity, 97%), respectively." (PMID 36339408, 2022). "Electrophysiological recordings, coupled with measurements of gene and protein expression in rat insulinoma cells were performed to investigate whether AMPK modulates glucose-sensing in insulin-secreting cells by altering phosphotransfer to KATP channels." (PMID 36232796, 2022). "A primary disease endpoint in TEDDY is islet autoimmunity (IA), defined as persistently positive for insulin autoantibodies (IAA), glutamic acid decarboxylase autoantibodies (GADA), or insulinoma-associated-2 autoantibodies (IA-2A) at two consecutive visits confirmed by the two TEDDY laboratories." (PMID 36123651, 2022). "Insulinomatosis is another rare cause of hyperinsulinemic hypoglycemia in adults and is characterized by the synchronous and metachronous occurrence of small insulinomas, multiple insulinoma precursor lesions, and small proliferative insulin-expressing monohormonal endocrine cell clusters (IMECCs)." (PMID 35406570, 2022). "The precise mechanisms underlying the excess amount of insulin secretion by the insulinomas and the impaired cellular response to hyopglycaemia are not well understood." (PMID 36288153, 2022). "Proglucagon co-expression with insulin is a feature of insulinomas." (PMID 35378291, 2022). "GAL opened adenosine triphosphate (ATP)-sensitive K+ channels and hyperpolarized cell membranes in the rat RINm5F insulinoma cell line, and the peptide blocked the activity of AC and the secretion of insulin via the interaction with Gαi1, Gαi2 and Gαi3 proteins." (PMID 35954419, 2022). "Interestingly, downregulation of Bbs5, Bbs7, and Bbs9 in the Min6 mouse insulinoma cell line LED to ~2-fold increase in insulin secretion." (PMID 35832432, 2022). "Insulinoma is a rare tumor resulting in insulin hypersecretion." (PMID 36494838, 2022). "Oleoyl lysophosphatidylcholine (LPC 18:1) binds to the membrane receptor of GPR119 on β-cells, regulating insulin secretion through a protein kinase A (PKA)-related signaling pathway, and promotes glucose-stimulated insulin secretion in murine NIT-1 insulinoma cells." (PMID 36557202, 2022). "An in vitro study reported that both aqueous and methanolic extracts from L. sibiricus aerial parts enhanced insulin secretion and insulinoma cell proliferation in rat insulinoma cells (INS-1E) through depolarization of the plasma membrane and an increase in the intracellular calcium concentration." (PMID 35956991, 2022). "Insulinomas in dogs also contain amphicrine cells expressing both insulin and pancreatic lipase." (PMID 36288153, 2022). "Clinical manifestations may change over the course of the disease and there are a number of factors that cause similar symptoms or test results (for instance, exogenous insulin intake or Hirata’s disease mimic insulinoma)." (PMID 36233409, 2022). "In the context of rat insulinoma cells, deficient for Wfs1, ibudilast, a canonical PDE4 inhibitor and NCS1 binding drug, has been used as an efficient treatment to restore calcium homeostasis, cell viability, and glucose-stimulated insulin secretion." (PMID 36320410, 2022). "The hypersecretion of insulin by insulinomas increases the blood insulin levels." (PMID 36288153, 2022). "In an in vitro approach, the expression of N-terminal HTT fragments with different polyglutamine lengths using an insulinoma cell line (INS-1E) showed that the glucose-stimulated induction of insulin release was significantly reduced when the insulinoma cell line expressed highly expanded HTT." (PMID 35682773, 2022).
insulinoma (continued). "Furthermore, ZnT7 is expressed in the islets of Langerhans in the mouse pancreas, and it has been demonstrated that ZnT7 overexpression in RIN5mf cells (rat insulinoma cells) increased insulin mRNA expression, insulin protein synthesis, and insulin secretion." (PMID 36233134, 2022). "The pNETs that arise are functional insulinomas that secrete insulin." (PMID 34199469, 2021). "A predominant PBA is chenodeoxycholic acid (CDCA), which in a recent study in our laboratory, showed significant excipient-stabilizing effects on microcapsules carrying insulinoma β-cells, in vitro, resulting in improved cell functions and insulin release, in the hyperglycemic state." (PMID 34572086, 2021). "Many CB1R antagonists (SR141716A, JD-5037, LH-21, AM251) also directly increased insulin release from mouse islets, clonal rat β-cells, mouse insulinoma βTC6 cells, and human islets and in isolated islets from both prediabetic and diabetic mice, concomitant with improved islet function." (PMID 34290671, 2021). "Silymarin also inhibits PDE-mediated breakdown of cAMP in HIT-T15 insulinoma cells, suggesting that increased and prolonged intracellular concentration of cAMP may enhance insulin exocytosis." (PMID 35098034, 2021). "In this model, the simian virus 40 (SV40) large T-antigen (Tag) oncogene is expressed under the control of the rat insulin gene promoter (Rip), leading to multifocal development of insulin-producing β-cell carcinomas (insulinoma) in the islets of Langerhans in the pancreas." (PMID 34638497, 2021). "CB1Rs are thought to play a role in focal adhesion kinase (FAK) phosphorylation because in INS-1E insulinoma cells FAK activation downstream of CB1Rs was found to make an essential contribution to cytoskeletal reorganization allowing for control of insulin release and potentially hypersecretion." (PMID 34290671, 2021). "For instance, quercetin can improve insulin production by rat insulinoma INS-1 cells in response to high glucose, as well as downregulate the relative expression levels of pro-apoptotic Bax and PDX-1 mRNAs, inhibit oxidative stress caused by H2O2, and reduce INS-1 cell apoptosis." (PMID 34824300, 2021). "A commonly utilized cell line for insulin secretion studies is the insulinoma cell line INS-1." (PMID 34940547, 2021). "In conclusion, the YY1 T372R mutation is often found in benign and malignant insulinomas but not in malignant PNETs that do not secrete insulin or in PDACs, suggesting that this mutation is specific for the diagnosis of insulinoma." (PMID 33985581, 2021). "These glucose-lowering effects may be modulated by increased insulin secretion, as seen in in vitro experiments using insulinoma cell lines and islets." (PMID 35098034, 2021). "The transdifferentiated PANC-1 and MIA PaCa-2 cells expressed 80.63% and 56.1%, respectively, of the INS mRNA levels seen in the insulin-producing human insulinoma cell line NT-3, while the abundance of SLC2A2 and MAFA transcripts was higher and lower, respectively, than in NT-3 cells." (PMID 34572891, 2021). "The importance of CFTR in insulin secretion has also been confirmed in a mouse insulinoma cell line, MIN6, where genetic or pharmacological inhibition of CFTR caused a reduction in insulin secretion that was further decreased in the presence of oxidative stress." (PMID 34566890, 2021). "Furthermore, the extract upregulated PDX-1 gene expression, contributing to increased gene transcription of insulin-like growth factor 2 (IGF-2) and insulin in INS-1 cells (rat insulinoma cell line, a β-cell line)." (PMID 34335803, 2021). "In addition, Kumawat and Kaur evaluated the insulinotropic effect of BCP and its combination with semi-essential amino acid L-arginine on insulin secretion in rat insulinoma (RIN-5F) cell lines following glucose challenge." (PMID 32998300, 2020).